AKT3 (AKT serine/threonine kinase 3)
Diseases named in the same sentence as AKT3 in open-access papers (continued):
Sharing a sentence is not in itself a finding about the gene and the disease.
cancer (continued). "Prognostic values of AKT1 and AKT3 That a higher expression of AKT3 appears as a marker of bad prognosis is not surprising for a kinase lying in the PI3K-AKT-mTOR pathway so important for cancer cell growth and survival." (PMID 38528080, 2024). "Additionally, LINC01405 upregulation led to the increased cell populations, proliferation, and upregulation of critical cancer‐related genes, including AKT1, AKT3, mTOR, WNT3A, SMAD3, CYCLIN D1, CYCLIN D2, BCL2, and GSK3B." (PMID 38225865, 2024). "Previous studies also indicated that, unlike Akt1 and Akt2 phosphorylation, Akt3 phosphorylation inhibits cancer cell proliferation." (PMID 38499532, 2024). "Survival meta-analysis showed that NUAK1, Akt isoforms (Akt1, Akt2, and Akt3), mTOR, and Rictor positively correlate with a high hazard ratio (HR) in BRCA, COAD, GBM, PRAD, STAD, and OV, the same types of cancer where NUAK1 correlates with EGFR expression and Akt Ser-473 phosphorylation." (PMID 38135881, 2023). "In this study, our network pharmacology results showed that AKT1, AKT3, and BCL2 are hub targets, and KEGG pathway enrichment analysis revealed that PI3K-AKT signaling pathway is involved in the effect of Aloin A against cancer-related muscle atrophy." (PMID 38180061, 2023). "Literature review found that circ_SAR1A, circ-EGLN3 and circ_001842 could promote the progression of RCC, while circ_AKT3 and circ_RPL23A exhibited the low expression in RCC and played important roles in cancer suppression." (PMID 36578555, 2022). "Furthermore, downregulation of AKT3 expression dramatically inhibited ESCC cell proliferation and migration, which were consistent with those seen in other cancers." (PMID 35443871, 2022). "AKT3 regulates “PI3K-Akt signaling pathway,” “Ras signaling pathway,” “Pathways in cancer,” “Rap1 signaling pathway,” “cGMP-PKG signaling pathway,” “Proteoglycans in cancer,” and “MAPK signaling pathway”." (PMID 34557357, 2021). "In addition, miR-582-5p has also been reported to inhibit tumorigenesis by targeting various oncogenic events through inhibiting AKT3, Rab27a, and TGF-β-SMAD in cancer models, supporting its function as a tumor suppressor." (PMID 33670427, 2021). "Collectively, our results have shown the involvement of AKT2, but not AKT1 and AKT3, in cancer cell migration and invasion thereby acquiring the characteristics of cancer stem cell." (PMID 33227065, 2020). "AKT comprises three isoforms (AKT1, AKT2, and AKT3), and the different isoforms are believed to mediate critical non-redundant or even opposing functions in cancer pathophysiology." (PMID 30012111, 2018). "In the same report, AKT3 has been suspected to be constitutively activated in a series of established cancer cells (no leukemic cells were included in this study), although the mechanism responsible for such a permanent activation remains unknown." (PMID 38528080, 2024). "AKT3 is frequently overexpressed in human cancers, and many regulatory oncogenic or tumor suppressor small non-coding RNAs (ncRNAs), including microRNAs (miRNAs), have recently been identified to be involved in regulating AKT3 expression." (PMID 37998329, 2023). "This is likely the reason why AKT3 expression was never linked to a particular CRIS class, even though that classification system specifically aims at describing pathways intrinsically active in cancer cells." (PMID 33673003, 2021). "Therefore, we want to emphasize that our work by no means rules out an oncogenic role of Akt3 in development of cancers of the mammary gland." (PMID 29282901, 2018).
cancer (continued). "For instance, AKT1, AKT2, and AKT3, belonging to the five pathways of signaling by GPCR, GPCR downstream signaling, innate immune system, adaptive immune system, and developmental biology, are three isoforms of AKT in PI3K/AKT pathway, which is an important drug target in many cancers including GBM." (PMID 30558539, 2018). "The expression of AKT2, AKT3, PKM2 and HK2 were significantly lower in the miR-29b agomir group compared with the NC agomir group, suggesting that miR-29b agomir treatment down-regulated in vivo AKT2/3 levels and further inhibited cancer cell glycolysis via downregulation of PKM2 and HK2 expression." (PMID 26512921, 2015). "Given the differential expression of AKT isoforms 1 and 2 and the low levels of expression of AKT3, the development of AKT 1/2 isoform selective inhibitors may be advantageous in cancer settings where the relative abundance of each isoform is specific to each cancer type." (PMID 36127435, 2022). "Considering that AKT3-174aa is one of the few negative regulators of PI3K/AKT signaling (others include PTEN, PHLPP, and CTMP), its expression level should be more intensively tested in larger cohort to confirm whether it is an independent biomarker for GBM or other types of human cancers." (PMID 31470874, 2019). "Lastly, they found that Akt1 and Akt3, but not Akt2, interact with DNA-PKcs in K-Ras mutant cells and stimulate DSB repair, thereby protecting cancer cell against IR." (PMID 33266502, 2020). "In four cases (AKT3, AR, MAPK1, and CTNNB1), we could observe a significant negative correlation in normal tissue, which was either non-significant or was significantly positive in cancer." (PMID 20920310, 2010).
infection (17 papers, 2010 to 2025). The state of being infected such as from the introduction of a foreign agent such as serum, vaccine, antigenic substance or organism. "We found that AKT1 and AKT2 were downregulated at the protein level during the acute phase of infection, but AKT3 was upregulated." (PMID 32977414, 2020). "We observed that AKT1 and AKT2 levels decrease over time as infection progressed, but AKT3 was dramatically increased at 120 hpi." (PMID 32977414, 2020). "By 32 weeks post-infection, small and medium sized tumors were detectable in only one of five Akt1−/− mice and while Akt3−/− mice had greater numbers of large tumors (>300 μm) compared to WT and Akt1−/− mice, this was not statistically significant." (PMID 24722238, 2014). "Furthermore, stable infection with lenti-UCA1-siRNA inhibited the expression of AKT3, p-AKT3, p-mTOR, and S6K, and increased the expression of EIF4E in BGC-823 cells, when compared with blank and negative control cells." (PMID 29212166, 2017). "Consequently, we observed a greater reduction to the number of attached, viable ESCs by combined Akt1/3 knockdown than by depleting Akt3 only at 3 and 6 days after lentiviral shRNA infection." (PMID 28483982, 2017). "Total cell lysates prepared from mouse lungs at 12, 20 and 32 weeks post-infection with AJEJJenv were probed by western blot with antibodies against Akt1, Akt2 and Akt3 to determine whether Akt isoform expression levels varied relative to normal lung." (PMID 24722238, 2014). "At 12 weeks post-infection with AJEJJenv, the Akt2−/− mice had a substantial and statistically significant greater number of small and medium sized lung tumors as compared to Akt3−/− mice, which had only a few detectable tumors, and WT and Akt1−/− mice, which had no detectable tumors." (PMID 24722238, 2014). "Interestingly, our data suggest that AKT3 is regulated by miR-29a upon infection." (PMID 23826261, 2013). "Studies have shown that AKT3 induced by IAV can inhibit FoxO1, and the FoxO pathway can inhibit IAVs infection by mediating anti-apoptosis and anti-inflammatory reaction." (PMID 34867371, 2021). "To genetically confirm the role of various AKT isoforms in macrophage infection, we knocked down the expression of AKT1, AKT2, and AKT3 in J774 macrophages." (PMID 24586159, 2014). "We observed the mRNA level of EGFR to be up-regulated, and downstream signaling protein, such as STAT3, STAT1, AKT3 and MKK4 also showed up-regulation at 4 days post infection." (PMID 21172007, 2010). "In addition, the PI3K-Akt signaling pathway-related genes were expressed at lower levels in SFTSV infection 24 and 48 h, for example, GP1BA, PIK3CA, PIK3CB, AKT3, PRKG1, and PRKG2." (PMID 37211158, 2023). "In addition, genes related to PI3K-Akt signaling pathway showed downregulation and inhibition at 48 h post-infection, such as GP1BA, PIK3CA, AKT3, and PLA2G4A." (PMID 37211158, 2023). "For validation of outlined interactions and to legitimate calculated miR-29a-target interactions and to prove biological significance, we examined the expression of miR-29a, AKT3, BAIAP2, COL4A1, VCL, CAV2 and CDC42 over the course of infection by means of RT-qPCRs." (PMID 23826261, 2013). "Furthermore, our RT-qPCR data showed that both predicted miR-29a targets AKT3 and BAIAP2 possessed an anti-correlated trend during early infection." (PMID 23826261, 2013). "In contrast, p38γ and particularly Akt (i.e., Akt1, Akt2 and Aktpan, but not Akt3) appeared strongly phosphorylated after infection with parental virus but only weakly after infection with ORF4−Tet+ (data not shown)." (PMID 20657771, 2010). "Infection with AKT2 or AKT3 did not rescue either WT or GRP94 KD cells from death (not shown)." (PMID 38811543, 2024). "Interestingly, the presence of either Akt2 or Akt3 does not affect sNAG stimulated wound repair and tensile strength as discussed here, or the clearance of infection and wound closure as previously reported." (PMID 25955155, 2015).
neurodevelopmental disorder (6 papers, 2019 to 2025). A behavioral and cognitive disorder with onset during the developmental period that involves impaired or aberrant development of intellectual, motor, or social functions. "Akt3, the dominant form of AKT in the brain, is associated with neurodevelopmental disorders and constitutes approximately half of total AKT protein in adult brains." (PMID 39763909, 2024).
adenocarcinoma (2 papers, 2023). A common cancer characterized by the presence of malignant glandular cells. "Furthermore, AKT2 and AKT3, as part of phosphoinositide 3-kinase (PI3K)/AKT/mTOR signaling pathway, have been associated with several adenocarcinomas." (PMID 36982700, 2023).
brain diseases (2 papers, 2019 to 2022). "Here, we report a case of a patient with a de novo germline AKT3 variant, NM_005465.7:c.233A > G, p.(Gln78Arg), who presented with CH in addition to typical AKT3-related brain disorders." (PMID 35665751, 2022). "Moreover, AKT3 mutations affecting the catalytic kinase domain have been associated with elevated kinase activity in brain diseases, thus impacting the enzyme activity." (PMID 30787430, 2019).
hematological disorders (1 paper, 2024). "Relationship between AKT3 and mutations related to MDS or MPN hematological disorders The MDS- or MPN-related mutations affect genes involved in different molecular aspects of gene expression including RNA splicing (SRSF2, U2AF1 and SF3B1), chromatin remodeling (ASXL1) and gene transcription (BCOR)." (PMID 38528080, 2024).
myopathy (1 paper, 2022). A disease of the muscle in which the muscle fibers do not function properly. "Using network analysis tools, we predicted the impact of the DE TEs on the expression of genes and found that amongst the genes potentially modulated by TEs, there are some previously associated to statin-linked myopathy pathways (e.g., AKT3)." (PMID 36613689, 2022).
AKT3 also shares sentences with these, for which no sentence is quoted: nasopharyngeal carcinoma (6 papers); clear cell renal cell carcinoma (4); psychiatric disorder (4); type 2 diabetes (4); cortical dysplasia (3); endometrial cancer (3); liver cancer (3); lung adenocarcinoma (3); bipolar disorder (2); fibrosarcoma (2); focal epilepsies (2); ischemic stroke (2); myocardial ischemia (2); neurodegenerative disease (2); serous ovarian cancer (2); abscess (1); acute leukemia (1); acute myocardial infarction (1); adenoid cystic carcinoma (1); alcoholic liver diseases (1); asthma (1); Azoospermia (1); basal cell carcinoma (1); benign tumor (1); Brain Abnormalities (1); capillary malformation (1); central nervous system diseases (1); cerebral infarction (1); chondrosarcoma (1); chronic myeloid leukemia (1).
A further 63 diseases each share a sentence with AKT3 in 1 paper.